CD47 (CD47 molecule)
Diseases named in the same sentence as CD47 in open-access papers (continued):
Sharing a sentence is not in itself a finding about the gene and the disease.
tumor (continued). "High CD47 expression on tumor cells acts as a “do not eat me” signal through binding to the inhibitory receptor SIRP-α on macrophages." (PMID 35035479, 2022). "A non-clinical study indicated that CD47 targeted monotherapy, or a combination with anti-PD-L1, preserves T cell bioenergetics and anti-tumor function, resulting in a decreased TNBC tumor burden." (PMID 36009390, 2022). "Tumour volume, tumour weight and tumour inhibition rate showed that cotargeting VEGF and CD47 could enhance potent antitumour effects." (PMID 35694254, 2022). "Tumor cells can evade clearance by macrophages through expressing innate immune checkpoint CD47 to convey a negative signal of phagocytosis." (PMID 35874757, 2022). "Furthermore, in tumor tissues, the expression of CD24, another known innate immune checkpoint, is notably strong compared to the expression of CD47." (PMID 35978372, 2022). "In contrast, DARA-IgA2, but not DARA-IgG1 achieved significantly higher tumor cell lysis in ADCC experiments with CD47 KO and QPCTL KO cells compared to MOLT-13 control cells." (PMID 36052078, 2022). "Moreover, HIF-1 induces the expression of CD47 which is a “don’t eat-me” signal (CD47/signal regulatory protein (SIRP)-α axis) that blocks prophagocytic signals and promotes tumor escape from immune surveillance." (PMID 35158804, 2022). "Consistently with tumor weight observations, the CaCE treatment group showed the highest survival rate, indicating a strong antitumor effect of the exosome facilitated the delivery of CCPD and CD47 antibodies." (PMID 36054073, 2022). "This anti-CD47 oncolytic adenovirus could induce durable tumor suppression by changing the TME condition and increasing activated TILs in the tumor site." (PMID 36311790, 2022). "To address this question, we examined tumor growth in pairs of wild-type and Cd47 knockout allografts, without systemic treatment with CD47-blocking antibodies." (PMID 36411318, 2022). "Combination blockade of CD47 and PD1, CTLA4 also achieved better anti-tumor effect." (PMID 35697717, 2022). "Bifidobacterium stimulates the production of anti-CD47 antibodies by activating the STING signaling pathway, which might alter the tumor microenvironment to achieve the effect of immunotherapy." (PMID 35844804, 2022). "These outcomes could rationalize using CD47 blockades in combination with CAR-T cells, providing a novel approach for effective tumor immunotherapy." (PMID 35978372, 2022). "Finally, dual checkpoint blockade of CD47 and LILRB1 was tested with MCL tumor cells isolated from two patients." (PMID 36389667, 2022). "All these events reduce surface exposure of the “do not eat me” signal CD47 after stimulation by BoxA, make tumor cells more visible to macrophages and elicit a robust phagocytosis." (PMID 36293358, 2022). "Histopathological examination confirmed that all 12 samples had UTUC, and no adverse effects of anti-CD47-Alexa Fluor 790 on tumor or normal uroepithelial histology were seen." (PMID 35295998, 2022). "However, the depletion of aCD47 by CD47 expressed on RBC and the resulting hematotoxicity (anemia, thrombocytopenia) hinder its application in tumor therapy 11-14." (PMID 35832081, 2022). "Nishiga and colleagues show therapeutic efficacy for a combination of radiotherapy and CD47 blockade, which also elicits an abscopal effect mediated by macrophages migrating into non-irradiated tumor sites and phagocytosing cancer cells." (PMID 36411318, 2022). "The number of CSCs with the EpCAM+CD44+MET+CD47+ phenotype increased with tumour progression, while no significant changes were found in the number of CSCs representing the main population of tumour cells." (PMID 35563449, 2022). "We designated “ImmunoGenic Surrender” (IGS), the mechanism whereby CXCR4 engagement drives CD47 surface depletion and eventually the appearance of tumor-specific CD8 T cell clones, as the tumor cells surrender to macrophages, which phagocytose them when still alive." (PMID 35565443, 2022).
tumor (continued). "Generally speaking, in the tumor microenvironment, when interacting with signal regulatory protein-alpha (SIRPα) which is expressed on macrophages, CD47 can realize the function of “do not eat me”." (PMID 36660426, 2022). "Following intravenous administration, the nanoformulation exhibited increased accumulation at the CD47 expressing tumor site than liposomes without anti‐CD47mAbs." (PMID 36257824, 2022). "AO-176 is an anti-CD47 antibody based on an IgG2 Fc domain that binds selectively to CD47 on tumor cells but not on other cells." (PMID 36293358, 2022). "Azelnidipine inhibits the innate checkpoint CD47/CD172a and the adaptive checkpoint TIGIT–CD112 pathways and has anti-cancer effects by increasing the infiltration and function of CD8+ T cell and macrophage tumor cell phagocytosis in vivo and in vitro." (PMID 35656508, 2022). "Both anti-CD47 mAbs clones showed similar anti-tumor activity and no statistical difference in survival rate was observed between STI-6643 and Hu5F9-treated animals." (PMID 35664753, 2022). "Previous studies have reported that NTP treatment can oxidize proteins on the cancerous cell surface (e.g., CD47, CD44), which may interrupt tumor survival or immune evasion." (PMID 36176603, 2022). "The phagocytic function of macrophages is regulated by the inhibitory receptor signaling regulatory protein α (SIRPα) expressed on macrophages, whose ligand is CD47, a “do not eat me” signal, overexpressed on tumor cells." (PMID 35965509, 2022). "In the ex vivo imaging experiments, all patients were pathologically diagnosed with UTUC, and no adverse effects of anti-CD47-Alexa Fluor 790 on the histological structure of the tumor and normal uroepithelium were observed." (PMID 35295998, 2022). "Unfortunately, blocking CD47‐SIRPα is not enough when the pro‐phagocytic molecule calreticulin (CALR) on tumor cells is low." (PMID 37323705, 2022). "CD47, a transmembrane protein known as a “do not eat me” signal, which is highly expressed on tumor cells, interacts with signal regulatory protein α (SIRPα) expressed on dendritic cells." (PMID 35784290, 2022). "Second, a detailed mechanism of CD47 expression involving tumor immune evasion in ccRCC has not been mentioned." (PMID 36291980, 2022). "The tumor-targeting analysis confirmed both EGFR and CD47 are good targets of TNBC." (PMID 35057042, 2022). "Therefore, combinations of tumor targeting antibodies with LILRB1 and either CD47 or SIRPα immune checkpoint inhibitors deserve further evaluation in animal models towards clinical application." (PMID 36389667, 2022). "Another emerging strategy to impede CD47/SIRPα interactions is the pharmacological inhibition of glutaminyl cyclases, especially glutaminyl-peptide cyclotransferase like protein (QPCTL), which is highly expressed in tumor cells." (PMID 36052078, 2022). "We only detected an obvious induction of CD47 expression in HOS, SJSA-1 and U-2 OS cells after incubation with conditioned medium of macrophage treated with doxorubicin in the presence of doxorubicin-treated tumor-conditioned medium (M-CMDOX/DOX)." (PMID 36274066, 2022). "In addition to promoting macrophage immunotherapy when used in combination with CD47/SIRPA blockers, BP nanoparticles can also be used to deliver drugs such as siRNA to increase M1 TAMs or inhibit M2 TAMs at tumor sites." (PMID 35859703, 2022). "However, in recent years, scholars have mostly focused their prognosis for patients on the impact of tumor cells or the tumor microenvironment, such as CD47 expression and CD163+ macrophages, cytokeratin-19 (CK-19), and tumor-infiltrating platelets." (PMID 36159473, 2022). "Our CD47 knockout is 100% (rather than incomplete per earlier studies), and a combination with the tumor-opsonizing IgG TA99 proves effective against established lung metastases of B16F10s." (PMID 35454837, 2022).
tumor (continued). "Although tumor cells produce EXOs with high levels of CD47, they are obviously not suitable for use as drug carriers in clinical practice." (PMID 35845399, 2022). "It has not been determined if tumor cells utilize the QPCTL enzyme to stabilize the CD47-SIRPα interaction." (PMID 35865547, 2022). "Using the Fluorescent 14-bit images from Zeiss Axioscan.Z1 slide scanning system, the penetrated rat anti-CD47 antibody was detected by interacting to rabbit anti-rat IgG and rhodamine red conjugated goat anti-rabbit antibody on the surface of GFP-labeled tumor cells." (PMID 35314680, 2022). "On the other hand, tumor cells can also protect themselves from phagocytosis by expressing the cell surface receptor CD47, known as an anti-phagocytic (“do not eat me”) signal." (PMID 35269922, 2022). "The role of CD47 expression as a ‘do not eat me’ signal that inhibits phagocytosis of tumor cells by macrophages is well established." (PMID 36291980, 2022). "Tumor stage was not related to the proportions of CD47+ tumor cells in the center / peripheral of the tumor, nor to the proportions of CD47+ TIICs." (PMID 36171566, 2022). "Radiotherapy was delivered focally to only the tumor on the right side of each mouse, with or without concurrent systemic anti-CD47 antibody treatment." (PMID 36411318, 2022). "These abscopal effects are independent of T cells but require macrophages that migrate into non-irradiated tumor sites in response to inflammatory signals produced by radiation and are locally activated by CD47 blockade to phagocytose cancer cells." (PMID 36411318, 2022). "Hypoxia modulates PD-L1, human leukocyte antigen g (HLA-G), CD47, and the immune checkpoint V-domain IG suppressor of T cell activation (VISTA) to form an inhibitory immune microenvironment, promoting immune escape of tumor cells." (PMID 36212414, 2022). "The nMOFs‐based RT generated ROS to induce the ICD effect by exposure of CRT on tumor cell surfaces as an “eat‐me” signal, and anti‐CD47 antibodies were released to block the “not‐eat‐me” pathway to promote antigens presentation." (PMID 35652198, 2022). "Bifidobacteria specifically targeted tumor tissues and the accumulation of Bifidobacteria in the TME improved the capability of tumor inhibition by CD47 blockade in mice nonresponders." (PMID 36726985, 2022). "Preclinical studies have shown that CD47 blockade is not sufficient for phagocytosis of tumor cells." (PMID 36497385, 2022). "Tumor cells, like normal cells, can express CD47, a “do not eat me” signal that prevents CD172a+ macrophages from phagocytosing them." (PMID 35656508, 2022). "LILRB1 inhibition combined with anti-CD47 monoclonal antibody treatment improved the macrophage phagocytosis and tumor-killing effects, without hurting normal cells." (PMID 35646915, 2022). "Interestingly, some works showed that human tumor cells escape the microglia immune surveillance by upregulating CD47 and SIRP ⍺ on tumor and microglial cells, respectively." (PMID 36411434, 2022). "Interestingly, we found exhausted CD4+ T cells expressed not only high levels of CD47 but also the ligand Galectin-9 in the TME of both plaque and tumor MF." (PMID 34885092, 2021). "CD47, a transmembrane protein found ubiquitously expressed on normal cells, has increased its expression in a high proportion of malignant tumor cells." (PMID 33802565, 2021). "CD47 expression was observed in a minority (16.2%) of CRA tissues and was significantly correlated with adverse clinicopathologic features, including lymphatic invasion, perineural invasion, tumor budding, the pN stage, and the AJCC stage." (PMID 33917794, 2021). "In parallel, tumor cells isolated from MCS–monocytes coculture expressed the “do not eat me” signal CD47 as well as PD-L1 and HLA molecules (HLA-A and HLA-B), which are recognized ligands for PD-1 and LILRB1, respectively." (PMID 33922336, 2021).
tumor (continued). "“Don’t eat me” signaling pathways, such as CD47-SIRPα, the MHC-I-LILRB1 axis, and the CD24-SIGLEC-10 axis can be expressed by all types of macrophages and play crucial roles in inhibiting macrophage phagocytosis of tumor cells in numerous cancer types." (PMID 34778091, 2021). "In this study, we successfully constructed CD47-functionalized exosomes that could evade MPS and enhance tumor targeting." (PMID 34373736, 2021). "Regarding the tumor cells, all dissociated tumors from all three patients contained cells expressing EpCAM and CD47, with and without positive CD56 expression." (PMID 33670410, 2021). "In LPS, the prognostic impact of CD47/SIRPα signaling in patients has not been reported, although many patients have been found to have CD47 expression in tumor cells, as well as infiltrating SIRPα positive macrophages." (PMID 33893830, 2021). "ATP acts as a “find me” signal, CRT acts as an “eat me” signal, and CD47 in tumor cells acts as a “do not eat me” signal." (PMID 34638242, 2021). "Selective targeting of tumor-overexpressed TSP-1 at the CD47-binding site rather than targeting the ubiquitous CD47 membrane receptor explains why TAX2 was found to be safe in rodents." (PMID 34638503, 2021). "Dual targeting CD47 and PD-L1 by fusion protein or bispecific antibody enables effective targeting to tumor cells than non-tumor cells, increased DNA sensing, DC cross-presentation, and anti-tumor T cell response." (PMID 34068552, 2021). "According to MPM patients, we also observed that both SIRPα and the “do not eat me” signal CD47 were, respectively, expressed by Mo-TAMs and tumor cells." (PMID 33922336, 2021). "In comparison to anti-CD47 or anti-PDL1 monotherapy or anti-CD47 + anti-PDL1 combinational therapy, simultaneously targeting both CD47 and PDL1 on tumor cells with a CD47/PDL1 bispecific antibody delivered the best tumor growth inhibition and prolonged recipient survival." (PMID 33790906, 2021). "Considering the functional interaction between TSP1 and CD47, we cannot rule out the idea that it contributes to stimulating tumor progression, by impairing tumor vasculature normalization and/or the immune response." (PMID 34439212, 2021). "It is designed to target both CD47 and CD20 on B cells but avoid binding to human RBCs, which could simultaneously act on the tumor disease targets and modulate the immune system." (PMID 34305918, 2021). "Tumor cells evade macrophage phagocytosis by expressing CD47 that sends “do not eat me signal” to phagocytic cells via interaction with macrophage signal regulatory protein alpha (SIRPα) receptor." (PMID 34988021, 2021). "These CD47 blocking antibodies also improve adaptive responses by enhancing antigen presenting capacity within the tumor microenvironment, promoting CD8+ T cell anti-tumor cytotoxicity." (PMID 34944878, 2021). "Moreover, RS17 polypeptide inhibited tumor growth in vivo, and the treatment effect of RS17 superior compared with that of the B6H12 anti‐CD47 antibody." (PMID 33629544, 2021). "CD47 surface functionalization (ExosCD47) made the exosomes effectively escape the phagocytosis of mononuclear phagocyte system (MPS), and thus increased the distribution in tumor tissues." (PMID 34373736, 2021). "CD47-SIRPα engagement results in a “do not eat me” signal that provides an immune escape pathway for tumor cells." (PMID 34572939, 2021). "Irradiation damages the tumor tissues and increases infiltration and SIRPα expression on MDSCs, and combined with azelnidipine that blocks CD47/SIRPα interaction, it can enhance MDSC cell-mediated phagocytosis of tumor cells, thereby remarkably inhibiting the tumor growth." (PMID 34068552, 2021). "However, further studies revealed that CD47 signaling in murine and human CD8+ T cells directly inhibits their antigen-dependent killing of tumor cells." (PMID 33925464, 2021).
tumor (continued). "Overexpression of CD47 in tumor cells compared to non-malignant cells has been demonstrated in multiple studies with various types of malignancies, which was believed to warrant cancer cells to exploit the “don’t eat me” function of CD47." (PMID 33765961, 2021). "Cell adhesion molecules such as ITGA3, CD47, MDK, ITGB1, CD55, and CDH1 show a trend of upregulation with pseudotime, indicating that cell-cell communications play an important role during the evolutionary process of tumor growth and progression." (PMID 35087839, 2021). "If M1 macrophages are considered anti-tumoral and with effective phagocytic functionality, molecules such as CD47 can be expressed by tumor cells and send a “do not eat me” signal to TAM." (PMID 33800593, 2021). "Our interest in the regulation of anti-tumor immunity by TSP1 began with the observation that TSP1 globally suppresses changes in gene expression that are induced by T cell antigen receptor (TCR) signaling, which we subsequently found to require CD47." (PMID 33925464, 2021). "We and others have reported that CD47 antibodies exhibit anti-tumor activities independent of SIRPα signaling." (PMID 33925464, 2021). "It is reported that a CD47/SIRPα blockade and TIGIT/PVR blockade could elicit significant anti-tumor responses." (PMID 34068552, 2021). "But compared with HT treatment, the combination of HT and anti-CD47 antibody did not further alleviate tumor weight." (PMID 34858184, 2021). "CD47 mediates tumor evasion by serving as a “do not eat me” marker and transmitting the anti-phagocytic signal to macrophages." (PMID 34068552, 2021). "Further investigation on the relationship between CD47 expression and CD163+ macrophages in tumor might assist to justify the efficacy of targeting CD47 therapeutic approach in PanNETs." (PMID 33765961, 2021). "The upregulation of the antiphagocytic (i.e., “do not eat me”) surface protein CD47 is a well-characterized immune evasion mechanism by tumor cells." (PMID 33919979, 2021). "CD40 agonists, PI3Kγ inhibitors, CD47 inhibitors, and a class IIa HDAC inhibitor have all been shown to reduce primary and metastatic murine breast tumors and have emerged as novel modalities to convert TAMs to anti-tumor macrophages." (PMID 33968034, 2021). "The addition of stromal cells increased transcription of matrix remodelling proteins FN1 and MMP9, induced release of tumour-promoting immune molecules MIF, Serpin E1, CXCL1, IL-8 and CXCL12 and altered cancer cell expression of immunotherapeutic targets EGFR, CD47 and PD-L1." (PMID 34885111, 2021). "In CD47 deficient mice, angiogenesis in xenograft tumor was enhanced, and the lack of CD47 accelerated tumor progression." (PMID 33765961, 2021). "Conversely, in the absence of CD8+ T cells, blocking CD47 does not inhibit tumor growth in syngeneic models, and genetic disruption of SIRPα signaling in macrophages did not impair syngeneic tumor growth." (PMID 33925464, 2021). "Antibodies dual blocking the innate checkpoint CD47 and adaptive checkpoint PD-L1 or TIGIT could achieve durable anti-tumor effects." (PMID 34068552, 2021). "The specific markers that we analyzed include tumor stem cell markers (CD24, CD44), markers of immunosuppression (CD47, PD-L1), markers of cell adhesion (CD49d, ICAM-1), markers of lymphocytes co-stimulation (CD80, CD86), and markers of antigen presentation (MHC class I, MHC class II)." (PMID 34411144, 2021). "Magrolimab tightly binds to human CD47 antigen and induces phagocytosis of tumor cells in a non-antibody dependent cellular cytotoxicity (ADCC) mechanism." (PMID 34584838, 2021). "Overexpression of CD47 was observed in all PanNET tumors, but the adjacent non tumor tissue (except islets) showed little to no staining." (PMID 33765961, 2021).